CRP (C-reactive protein)
Diseases named in the same sentence as CRP in open-access papers (continued):
Sharing a sentence is not in itself a finding about the gene and the disease.
Sepsis (continued). "There is much evidence to prove CRP and procalcitonin as independent markers for the diagnosis of sepsis in children." (PMID 40351994, 2025). "CRP levels on postoperative day 3 were significantly elevated in the sepsis group (P<0.001), and a similar trend was observed on postoperative day 5 (P<0.001)." (PMID 40761819, 2025). "Established biomarkers, including lactate, CRP, PCT, WBC, NLR, and PSP, are valuable diagnostic and prognostic tools for sepsis, but are limited by specificity and response timing." (PMID 41007875, 2025). "This systemic inflammation is prevalent in sepsis, and is characterized by elevated inflammatory markers such as C-reactive protein (CRP), tumor necrosis factor-alpha (TNF-α), and interleukin-6 (IL-6)." (PMID 40098009, 2025). "Nowadays, some biomarkers, including procalcitonin and C-reactive protein, have been applied for the diagnosis and evaluation of sepsis (Mirijello, Tosoni & On Behalf of the Internal Medicine Sepsis Study Group, 2020)." (PMID 40028203, 2025). "Future research should focus on standardizing cfDNA measurement techniques and discovering its role alongside CRP in various acute settings, such as sepsis, myocardial infarction, and exercise." (PMID 40282303, 2025). "Plasma CRP concentrations at presentation were above the upper reference limit of the laboratory (10.5 mg/L) in all dogs with nSIRS or sepsis." (PMID 40607352, 2025). "In sepsis, cfDNA correlates strongly with disease severity and prognosis, outperforming CRP in early diagnosis." (PMID 40282303, 2025). "Concerns were expressed of possibly missing the CRP peak and cases of serious sepsis, reinforcing the hesitancy of relying on a single test and emphasising that follow-up planning is still required." (PMID 41009893, 2025). "Multivariate analysis identified elevated CRP and leukocyte levels as significant predictors of sepsis." (PMID 40142700, 2025). "Among the current clinical markers of sepsis (including lactate, C-reactive protein, etc.), lactate is the most commonly used biomarker to recognize sepsis, but it is still not specific and does not realistically reflect changes in the condition." (PMID 39854580, 2025). "Our study reveals that combining immune cell ratios and CRP significantly enhances early detection of pediatric sepsis, improving clinical outcomes." (PMID 40755920, 2025). "When used together, PCT and CRP demonstrated 85% sensitivity and 80% specificity in predicting sepsis." (PMID 41011807, 2025). "Compared to the control group, the sepsis group exhibited higher APACHE II scores, SOFA scores, serum Lac, CRP, PCT levels, VDR Fok I (rs2228570) locus f allele and VDBP rs4588 locus A allele frequencies, and lower vitamin D levels (P < 0.05)." (PMID 40370697, 2025). "Hematologic parameters, pPCT and CRP were assessed on days 1, 2 and 3 in healthy dogs and on days 1, 2, 3 and 4 in dogs with nSIRS or sepsis." (PMID 40607352, 2025). "CRP/Albumin ratio>2 presented the highest sensitivity and specificity in the prediction of 90-day mortality in patients with sepsis/septic shock." (PMID 40091950, 2025). "We also investigated two reference biomarkers, PCT and CRP, used for many years to assist clinicians in the diagnosis of sepsis." (PMID 41301767, 2025). "Receiver operating characteristic (ROC) curve evaluation revealed a low predictive level for PCT and CRP in burn sepsis prognostic value, while BNP showed good predictive value (p < 0.05)." (PMID 39982339, 2025). "Established biomarkers (CRP and procalcitonin) used in the diagnosis of sepsis have been shown to be elevated during the acute sepsis phase, reaching their maximal concentration at 48 h after the initial trigger." (PMID 41464744, 2025). "CRP is a useful biomarker for the early detection of sepsis, offering high sensitivity but limited specificity." (PMID 41011807, 2025).
Sepsis (continued). "The study’s innovative aspect lies in its focus on glycemic control, inflammatory markers (CRP), and their role in predicting postoperative sepsis, a critical concern in T2DM patients." (PMID 40761819, 2025). "CRP provides useful information on a wide range of cardiovascular events and inflammatory conditions, including sepsis, and has analytical advantages as a “robust biomarker” that is minimally affected by sample or environmental conditions." (PMID 41225969, 2025). "The protocol also included adding antifungal agents as prophylaxis for patients at risk of fungal sepsis, withdrawing microbiological cultures for all patients suspected to have sepsis, and regular assessment of antibiotic response by CRP testing." (PMID 40988069, 2025). "In contrast, median plasma CRP concentrations were markedly above the reference range in dogs with nSIRS and sepsis at admission." (PMID 40607352, 2025). "Because of its high specificity, CRP is still a helpful adjuvant, particularly when ruling out sepsis." (PMID 40242671, 2025). "Compared to traditional markers like CRP, PCT, and white blood cell count (WBC), IL-18 has demonstrated better diagnostic discrimination for sepsis and septic shock." (PMID 40510342, 2025). "CRP is a well-established sepsis biomarker that can predict sepsis mortality and ICU LOS, especially with serial measurements." (PMID 40731775, 2025). "The AUC to discriminate sepsis from NIOF was highest for CRP (AUC, 0.843), followed by sCD25 (AUC, 0.746), sTREM-1 (AUC, 0.655), Gal-9 (AUC, 0.638), and lactate (AUC, 0.519)." (PMID 41225969, 2025). "This study included a neonatal cohort comprising 105 individuals (51 healthy controls and 54 neonates with evidence of sepsis (as judged by clinical evidence and/or CRP or IL-6 elevation)." (PMID 39937751, 2025). "The use of CRP measurements in the prognosis of sepsis has been widely described in the available literature." (PMID 40507966, 2025). "During the last chemotherapy, PCT was highly elevated (>100 ng/mL), usually observed in severe sepsis or septic shock, whereas CRP was moderately elevated (<50 mg/L)." (PMID 40419900, 2025). "Studies have shown the importance of MDW as a reliable diagnostic marker for the early detection of sepsis compared to classic biomarkers such as PCT and CRP in various patient populations." (PMID 40005792, 2025). "Among patients with sepsis, higher abundance of CD38high Mono was associated with the SOFA score, C‐reactive protein (CRP), and APACHE II, highlighting its potential pathophysiological significance in sepsis." (PMID 40145840, 2025). "When used together, IL-6 and CRP demonstrated 67% sensitivity and 62% specificity in predicting sepsis." (PMID 41011807, 2025). "Sepsis groups showed significantly elevated levels of acute-phase reactants, including CRP, SAA1, and SAA2, reflecting the immediate immune response to infection of the host." (PMID 40864331, 2025). "We also report the performance of state-of-the-art baselines monocyte distribution width (MDW), CRP, Sepsis Index, Mindray SVM, and Conformal Multidimensional Prediction of Sepsis Risk (COMPOSER)." (PMID 40009841, 2025). "While CRP is a reliable marker of inflammation, it lacks specificity for sepsis, as elevated CRP levels occur in multiple inflammatory diseases." (PMID 39858517, 2025). "Our review compares the use of CRP and cfDNA in myocardial infarction, sepsis, and physical exercise, focusing on their origins, kinetics, and clinical utility." (PMID 40282303, 2025). "He had clinical instability prompting suspicion of sepsis on multiple occasions, but only elevated C-reactive protein (CRP) peaking at 28 mg/L on day 11 of life with multiple negative blood cultures." (PMID 41141211, 2025). "After logistic regression, it was found that RDW, APACHE II score, PCT, IL-6, CRP, and cystatin C were all independent risk factors for AKI in children with sepsis (P<0.05)." (PMID 41281283, 2025).
Sepsis (continued). "Obviously, CRP level (OR 1.01, p = 0.003) and leukocyte count (OR 1.16, p = 0.004) were significant predictors of sepsis, confirming the role of inflammatory markers in identifying patients at risk for systemic infection." (PMID 40142700, 2025). "The molecular and cellular basis of anti-bacterial function of CRP is mostly characterized in mouse sepsis model." (PMID 41214213, 2025). "Our patient's presentation with feeding intolerance and clinical instability, accompanied by an elevated CRP and fluctuating white blood cell counts, led to multiple courses of antibiotics for suspected sepsis, which confounded the clinical picture." (PMID 41141211, 2025). "The AUCs for ROC curve analysis in predicting culture-positive sepsis were 0.72 (95% CI: 0.58 to 0.86, p = 0.002) for serum CRP and 0.83 (95% CI: 0.70 to 0.97, p = 0.0001) for salivary CRP." (PMID 40871545, 2025). "In sepsis, while CRP is derived from the liver, cfDNA primarily originates from damaged host cells, such as neutrophils and macrophages; it can also amplify the inflammatory response by activating TLR receptors." (PMID 40282303, 2025). "Significant increases in procalcitonin, CRP, and lactate levels in the sepsis group confirm the central role of these biomarkers in the infection and inflammation response." (PMID 41315982, 2025). "Traditional biomarkers of sepsis, such as C-reactive protein (CRP) and procalcitonin (PCT), are typically elevated postoperatively due to surgical trauma, limiting their specificity for infection diagnosis." (PMID 40863214, 2025). "CRP, a well-established biomarker for the early diagnosis of sepsis, has extensively been used in clinical settings." (PMID 40416430, 2025). "In sepsis, CRP levels can increase significantly, often correlating with disease severity and systemic inflammatory response." (PMID 40310418, 2025). "CRP blood concentrations, as crucial component of the acute phase response, can rise up to 1000-fold after trauma and sepsis." (PMID 39773175, 2025). "C-reactive protein (CRP) and procalcitonin (PCT) are widely used to support the early identification and diagnosis of sepsis; however, their diagnostic and prognostic performances have limitations." (PMID 41153306, 2025). "Our multivariate analysis further confirmed CRP and leukocyte count as significant predictors of sepsis, underscoring the importance of close monitoring in high-risk patients." (PMID 40142700, 2025). "Procalcitonin (PCT), lactate, C-reactive protein (CRP), and platelet count are among the key biomarkers frequently used in the diagnostic and prognostic evaluation of sepsis." (PMID 41464553, 2025). "Nevertheless, CRP is unsuitable for early screening and prognosis prediction of sepsis due to its delayed elevation during inflammation." (PMID 40687411, 2025). "In these patients, CRP and IL-6 were found to increase due to sepsis, and its effect on prognosis was emphasized." (PMID 40005437, 2025). "In terms of biochemical markers, higher postoperative levels of CRP, FPG, and HbA1c were associated with sepsis development." (PMID 40761819, 2025). "At our center, among infants with suspected early-onset sepsis, a LP was performed when there were clinical signs of meningitis, a positive blood culture, or increasing CRP." (PMID 41009903, 2025). "This device also simultaneously reduces endogenous inflammatory factors such as CRP in the serum of sepsis patients." (PMID 41145817, 2025). "In such contexts, a lack of required equipment, specialized staff, and necessary resources prevents use of routine tests such as blood cultures or the CRP test for sepsis identification." (PMID 39937751, 2025). "The results confirmed that serum levels of ACSL4 and GPX4 possess high diagnostic and differential diagnostic values for sepsis, comparable to the SOFA score, CRP, and PCT, and superior to the APACHE II score and GCS score." (PMID 40264754, 2025).
Sepsis (continued). "A prediction model for sepsis was constructed by combining sTREM-1, CRP, and a leukogram via a Bayesian network." (PMID 40806505, 2025). "The patient’s clinical deterioration was attributed to progressive kidney pathology and hospital-acquired infection resulting in sepsis, evident from a sharp rise in CRP and requiring inotropic support." (PMID 40698215, 2025). "Combination medications were administered to patients with documented or suspected bacterial co-infections (e.g. pneumonia, sepsis) based on clinical symptoms, laboratory markers (e.g. elevated CRP, leukocytosis), or imaging findings." (PMID 41219178, 2025). "And the problem with CRP...We know that it lags and can take up to 72 h to be demonstrating its peak...if we rely on it too heavily...we miss cases of serious sepsis." (PMID 41009893, 2025). "To further explore the clinical applications of mCD39, we compared patients' mCD39 with mHLA–DR, WBC, CRP, and PCT as diagnostic indicators to assess its predictive value in sepsis." (PMID 40065471, 2025). "During the early phase of sepsis, acute-phase reactants like C-reactive protein and inflammatory cytokines surge, amplifying the immune response." (PMID 40649892, 2025). "Even in cases of early-onset sepsis in neonates, the sensitivity of CRP measurements immediately after birth is known to be unreliable." (PMID 40809608, 2025). "Recent studies evaluate C-reactive protein (CRP) in the ED for early diagnosis and prediction of sepsis progression." (PMID 40685448, 2025). "Calprotectin had a lower AUC (0.61, 95% CI 0.59–0.62) than CRP (0.72, 95% CI 0.71–0.73) in distinguishing sepsis from non-sepsis (p < 0.001)." (PMID 40319081, 2025). "This study evaluated the individual and combined diagnostic accuracies of CRP, PCT and NRBCs for predicting the occurrence and severity of sepsis in the pediatric population." (PMID 40895306, 2025). "Biomarkers such as CRP and procalcitonin, although useful for assessing sepsis and monitoring treatment, lack specificity for diagnosing IE." (PMID 39817263, 2025). "Many studies have been conducted to determine the diagnostic accuracy of CRP and PCT in detecting infections and sepsis." (PMID 40471473, 2025). "Serum procalcitonin (PCT) and high-sensitivity C-reactive protein (hs-CRP) are still used as gold standard inflammatory parameters in the clinical evaluation of sepsis." (PMID 41462865, 2025). "In clinical practice, C-reactive protein (CRP) and procalcitonin are the most used sepsis biomarkers." (PMID 40009841, 2025). "During acute sepsis, patients had elevated peak C-reactive protein levels (CRP; 244 mg/L), white cell counts (16.5 × 109/L [IQR: 12.0–22.9]) and high sensitivity cardiac troponin T (hs-cTnT) levels (108 ng/L)." (PMID 40427008, 2025). "This tug-of-war involves not just IL-6, but a chorus of markers, like tumor necrosis factor-alpha (TNF-α), which kickstarts the cytokine storm, and C-reactive protein (CRP), a downstream signal of inflammation, all shaping sepsis’s chaotic course." (PMID 40149943, 2025). "A review of 258 sepsis biomarkers reported that most biomarkers were evaluated together or compared with CRP and/or procalcitonin." (PMID 40172393, 2025). "The diagnosis of sepsis in patients is determined by microbiological evidence such as blood culture, imaging examinations, and laboratory tests: elevated levels of CRP and dynamic changes in SOFA scores." (PMID 40703270, 2025). "Owing to its high sensitivity, rapid kinetics, and temporal resolution, HBP has shown superior diagnostic performance compared to traditional markers such as C-reactive protein (CRP) in a range of infectious diseases, including sepsis and pneumonia." (PMID 41459156, 2025). "A 2025 prospective cohort study demonstrated that the trend of CRP changes during hospitalization has good discriminatory ability in predicting mortality among sepsis patients." (PMID 41393139, 2025).
Sepsis (continued). "The area under the receiver operating curve (AUROC) to diagnose sepsis was 0.61 for calprotectin compared to 0.72 for CRP (p < 0.001)." (PMID 40319081, 2025). "During the acute sepsis episode, patients had elevated C-reactive protein levels (CRP; peak 270 ± 134 mg/L) and white cell count (peak 18.5 × 109/L [IQR: 14.5–26.4])." (PMID 40310393, 2025). "Its combination with CRP has demonstrated potential to distinguish viral from bacterial infections, further enhancing early sepsis stratification." (PMID 40685448, 2025). "Sepsis-specific determinants such as fungal infection, vasopressor requirement, and high inflammatory markers (e.g., high levels of C-reactive protein (CRP)) had a more significant role in developing NOAF in sepsis." (PMID 40621331, 2025). "CRP levels exhibit a significant effect on the development of sepsis in both univariate and multivariate analyses." (PMID 41011807, 2025). "In conclusion, our study reveals that combining immune cell ratios and CRP significantly enhances early detection of pediatric sepsis, improving clinical outcomes." (PMID 40755920, 2025). "Current protocols for diagnosing pediatric sepsis and septic shock rely on clinical criteria and biomarkers, such as C-reactive protein (CRP), procalcitonin (PCT), and white blood cell (WBC) counts." (PMID 40895306, 2025). "In sepsis, procalcitonin is released by various cells and tissues, including the liver, and, like CRP, its production is induced by IL-6, alongside other inflammatory cytokines and lipopolysaccharide." (PMID 41007672, 2025). "The AUC to discriminate septic shock from sepsis was highest for lactate (AUC, 0.751), followed by sTREM-1 (AUC, 0.624), Gal-9 (AUC, 0.614), sCD25 (AUC, 0.607), and CRP (AUC, 0.559)." (PMID 41225969, 2025). "We also assessed the relationship between circulating NETs and inflammatory biomarkers commonly used in sepsis management (e.g., CRP, PCT, and lactate), as well as emerging biomarkers such as IL-6 and MR-proADM." (PMID 41229414, 2025). "Clinicians currently rely on several readily available laboratory markers to assess disease severity and prognosis in sepsis, including white blood cell count, C-reactive protein (CRP), procalcitonin, and lactate." (PMID 41439926, 2025). "Several studies have demonstrated that PSP rises earlier than CRP or PCT in the onset of sepsis, and its levels correlate with disease severity and mortality." (PMID 40863214, 2025). "Marked neutrophilia and thrombocytopenia, along with high procalcitonin and C-reactive protein levels, indicate severe infection and possible septicemia." (PMID 40236343, 2025). "Several studies show PCT to be superior to CRP in differentiating invasive infections such as sepsis from viral infections, especially early in the disease course." (PMID 40025449, 2025). "In terms of diagnosing sepsis patients with ICU non-sepsis patients, MT-ND6 showed an acceptable diagnostic value (AUC = 0.789) when compared with the PCT (AUC = 0.797) and CRP (AUC = 0.791), and the best AUC was observed for SOFA score (AUC = 0.870)." (PMID 39611143, 2024). "Univariable analyses revealed significant associations of HSA with PNA, GA, BW, current weight, total and direct bilirubin, total plasma proteins, respiratory support, mechanical ventilation, sepsis, ibuprofen use, and C-reactive protein (p-values < 0.05)." (PMID 39394426, 2024). "We found the magnitude of the inflammatory response, quantified with peak CRP within 7 days of BSI, was associated with sepsis mortality." (PMID 38680606, 2024). "In the same prospective study of 60 thermal burn patients, researchers found that an increase in serum CRP concentrations predicted sepsis with an efficacy of 87%, a sensitivity of 93%, and a specificity of 80%." (PMID 39716257, 2024). "The biomarker combination of IL-6 and CRP, measured at the time of sepsis suspicion, had the highest overall sensitivity (92%), but the lowest overall specificity (79%) in the subgroup analysis." (PMID 38671704, 2024).